NDUFS6 (NADH:ubiquinone oxidoreductase subunit S6)
Description:
Accessory subunit of the mitochondrial membrane respiratory chain NADH dehydrogenase (Complex I), that is believed not to be involved in catalysis. Complex I functions in the transfer of electrons from NADH to the respiratory chain. The immediate electron acceptor for the enzyme is believed to be ubiquinone.
Synonyms: CI-13kD-A; CI-13kA; CI13KDA; MC1DN9
Tractability: Small molecule: an approved drug acts on it; a structure with a bound ligand is known. Antibody: UniProt places it where antibodies can reach, with high confidence. PROTAC: ubiquitination databases record sites on it; its protein half-life has been measured.
Target class: Enzyme; Oxidoreductase
Gene: Protein-coding gene on chromosome 5 (1,801,363 to 1,816,051, forward strand). Ensembl gene ENSG00000145494.
Subcellular location: Mitochondrion inner membrane
Pathways (Reactome):
Metabolism: Complex I biogenesis; Respiratory electron transport
Gene Ontology:
Molecular function: electron transfer activity; NADH dehydrogenase (ubiquinone) activity
Biological process: aerobic respiration; mitochondrial electron transport, NADH to ubiquinone; proton motive force-driven mitochondrial ATP synthesis; proton transmembrane transport
Cellular component: mitochondrial inner membrane; mitochondrion; respiratory chain complex I
Genetic constraint (gnomAD): Loss-of-function variants: 14 observed, 14.14 expected, observed/expected ratio (o/e) 0.99, 90% interval 0.65 to 1.54. The synonymous counts are far from expectation, so gnomAD's model fits this gene poorly and the ratio says little. Missense variants: 206 observed, 166.5 expected, observed/expected ratio (o/e) 1.24, 90% interval 1.1 to 1.39. Synonymous variants: 95 observed, 70.23 expected, observed/expected ratio (o/e) 1.35, 90% interval 1.14 to 1.6.
Gene-disease validity (ClinGen):
ClinGen rates the evidence that NDUFS6 causes each of these diseases.
mitochondrial disease (autosomal recessive): Definitive.
Homologues: Orthologues: dog NDUFS6 (85% identical), chimpanzee NDUFS6 (85% identical), pig NDUFS6 (81% identical), guinea pig NDUFS6 (80% identical), mouse Ndufs6 (79% identical), macaque NDUFS6 (77% identical), rat Ndufs6-ps1 (76% identical), tropical clawed frog ndufs6 (66% identical), zebrafish ndufs6 (65% identical), Drosophila melanogaster ND-13A (48% identical), Caenorhabditis elegans nduf-6 (43% identical).
Diseases named in the same sentence as NDUFS6 in open-access papers:
NDUFS6 is named in the same sentence as 43 diseases in open-access papers, as found by Europe PMC text mining. Sharing a sentence is not in itself a finding about the gene and the disease. The quoted sentences say what the papers report.
breast carcinoma (5 papers, 2017 to 2025). "Higher expression of MRPS12 and NDUFS6 correlates with decreased metastasis-free survival in breast cancer." (PMID 40909564, 2025). "The negative correlation between RORα expression and mRNA levels of NDUFS6 and NDUFA11 suggests that these two genes are the major targets of RORα mediating its function in ROS regulation during breast cancer progression." (PMID 34639006, 2021). "We showed that silencing NDUFS6 and NDUFA11 suppressed superoxide and ROS generation in breast cancer cells." (PMID 34639006, 2021). "We also found that the expression of RORα negatively correlated with NDUFS6 and NDUFA11 mRNA levels in human breast cancer tissue (TCGA breast cancer dataset)." (PMID 34639006, 2021). "In addition, the upregulation of complex I subunits in RORα-silenced mammary epithelial cells was accompanied by reduced OCR, while silencing NDUFS6 and NDUFA11 increased OCR in breast cancer cells." (PMID 34639006, 2021). "We also found that silencing NDUFS6 and NDUFA11 increased OCR in breast cancer cells." (PMID 34639006, 2021). "Most importantly, there are several genes that can distinguish the four breast cancer subtype as specific therapeutic targets for each subtype, including EFCAB2 for luminal A, ATG16L2 for luminal B, C1QTNF6 and NDUFS6 for HER2+, as well as CHERP, TIAM1, and GABRP for TNBC." (PMID 28245581, 2017).
malignant melanoma (4 papers, 2017 to 2024). "And BSG participated in regulating complex I activities and apoptosis in melanoma via interacting with mitochondrial NDUFS6." (PMID 38484369, 2024). "NDUFS6 plays an important role in regulating mitochondrial complex I activity and the mitochondrial apoptotic pathway in human malignant melanoma cells." (PMID 34150879, 2021). "Miho Hatanaka found melanoma cell growth was inhibited by CD147 silencing, Luo Z reported CD147 regulates mitochondrial apoptotic pathway in human malignant melanoma cells by interacting with NDUFS6." (PMID 28445958, 2017). "As an interacting partner with mitochondrial OSMR or CD147, NDUFS1/2 or NDUFS6 confers their individually roles in mediating oxidative phosphorylation related IR resistance of brain tumor stem cells, or in regulating complex I activity and apoptosis in human melanoma, respectively." (PMID 37469574, 2023).
axonal neuropathy (3 papers, 2024 to 2026). Any nerve disorder affecting the axon of a nerve. "We identified 5 patients from 3 families presenting with slowly progressive axonal peripheral neuropathy as their predominant symptom and carrying a homozygous NDUFS6 c.309+5G>A variant." (PMID 38459834, 2024). "Here, we identified a homozygous variant (c.309 + 5 G > A) in NDUFS6 in one male patient with axonal neuropathy accompanied by loss of small fibers in skin biopsy and further complicated by optic atrophy and borderline intellectual disability." (PMID 38217609, 2024).
Leigh syndrome (3 papers, 2024 to 2026). A progressive neurological disease defined by specific neuropathological features associating brainstem and basal ganglia lesions. "Biallelic variants in NDUFS6, encoding an accessory subunit of mitochondrial complex I, were initially associated with lethal neonatal mitochondrial encephalopathy and Leigh syndrome." (PMID 41683799, 2026). "Bi-allelic NDUFS6 variants have been linked with a severe disorder mostly reported as a lethal infantile mitochondrial disease (LMID) or Leigh syndrome (LS)." (PMID 38217609, 2024). "Strikingly, the NDUFS6 c.309+5G>A variant was previously reported to cause Leigh syndrome associated with death in the first year of life." (PMID 38459834, 2024). "We describe 3 families with Charcot-Marie-Tooth neuropathy (CMT), harboring a homozygous NDUFS6 NM_004553.6:c.309+5G>A variant previously linked to fatal Leigh syndrome." (PMID 38459834, 2024). "Biallelic loss-of-function variants in NDUFS6 (HGNC:7713) cause severe CI deficiency (MIM 618232) and Leigh syndrome." (PMID 38459834, 2024).
neuropathy (3 papers, 2024 to 2026). A disorder affecting the nervous system that manifests with pain, tingling, numbness, and/or muscle weakness. "While neuropathy has previously been reported primarily in association with the recurrent splice-site variant c.309+5G>A, our findings demonstrate that truncating NDUFS6 mutations can also underlie a neuropathy-predominant phenotype." (PMID 41683799, 2026). "Here, we report a patient with a novel homozygous truncating NDUFS6 variant presenting with a neuropathy-predominant phenotype accompanied by epilepsy, in the absence of neonatal metabolic decompensation." (PMID 41683799, 2026). "Together with previously published cases, our findings support a phenotypic heterogeneity ranging from lethal encephalopathy to neuropathy and reinforce the role of NDUFS6 as a disease-causing gene for inherited peripheral neuropathy." (PMID 41683799, 2026). "However until this approach will become the standard diagnostic test we recommend that NDUFS6 together with other mitochondrial genes (including SCO2 and SURF1) should be included in panels for molecular genetic testing of neuropathies, intellectual disabillity and optic atrophy." (PMID 38217609, 2024).
cardiomyopathy (2 papers, 2023 to 2025). A disease of the heart muscle or myocardium proper. "Our study underscores the efficacy and safety, as well as the therapeutic timeframe of AAV9-hNdufs6 therapy on Ndufs6-deficient cardiomyopathy." (PMID 40399258, 2025). "Secondly, further extensive long-term studies are warranted to fully elucidate the sustained therapeutic effects of AAV9-hNdufs6 in cardiomyopathy with Ndufs6 deficiency." (PMID 40399258, 2025). "Ndufs6 knockdown mice: • cardiomyopathy, systolic dysfunction, • renal disease associated with ultrastructural changes." (PMID 38234606, 2023). "Therefore, a typical model with gene trap-induced Ndufs6 deficiency was used in this study to mimic the cardiomyopathy caused by mitochondrial CI dysfunction due to Ndufs6 mutations." (PMID 40399258, 2025).
endometritis (2 papers, 2024 to 2025). An acute or chronic, usually bacterial infectious process affecting the endometrium. "In buffaloes with endometritis, NDUFS6 was expressed at significantly lower levels." (PMID 40711280, 2025). "The following genes were assessed for their expression levels using real-time PCR in both the normal and endometritis-affected buffaloes: immune (TLR4, IL-8, IL-17, NFKB, SLCA11A1, and NCF4) and antioxidant (SOD, CAT, NDUFS6, Nrf2, Keap1, PRDX2, HMOX1, OXSR1, ST1P1, and SERP1)." (PMID 39195794, 2024).
breast tumours (1 paper, 2023). "Therefore, we analysed the expression of 6 genes from the OXPHOS signature (AIFM1, NDUFV1, NDUFAB1, NDUFA7, NDUFS6 and MRPS12) among the most enriched in metastatic samples, by RT-PCR in specimens of 503 breast tumours patients with a follow-up of 20 years." (PMID 37452026, 2023).
cervical cancer (1 paper, 2012). A primary or metastatic malignant neoplasm involving the cervix. "Ndufs6 is an oxidative phosphorylation enzyme linked to cervical cancer." (PMID 22260314, 2012).
diabetic cardiomyopathy (1 paper, 2025). Diabetic cardiomyopathy is a disorder of the heart muscle in people with diabetes. "The KEGG enrichment results indicated that the knockout of Ndufs6 gene in heart may be involved in cardiac-related diseases, such as diabetic cardiomyopathy and cardiac muscle contraction." (PMID 40399258, 2025).
FINCA syndrome (1 paper, 2022). "The patient in this study had MCID due to a novel homozygous mutation in NDUFS6 and FINCA syndrome due to a novel compound heterozygous mutation in NHLRC2." (PMID 35801790, 2022). "The patient has MCID due to a novel mutation in NDUFS6 and FINCA syndrome due to novel mutations in NHLRC2, which is the main reason for the rapid onset and quick death of the patient." (PMID 35801790, 2022).
heart failure (1 paper, 2019). Inability of the heart to pump blood at an adequate rate to meet tissue metabolic requirements. "Inhibition of complex I through knockdown of the gene for the complex I subunit Ndufs6 leads to decreased ATP production and heart failure as well." (PMID 30838215, 2019).
malignant fibrous histiocytoma (1 paper, 2012). "In the literature, a gain of 5p has been found in osteosarcoma and malignant fibrous histiocytoma, and studies combining aCGH and gene expression assays suggest that 5pter-p15.3 harbors several candidate oncogenes including TRIP13, TERT, NDUFS6, and ADAMT16." (PMID 22551002, 2012).
mastitis (1 paper, 2025). Inflammation of breast tissue during lactation or postpartum due to an obstructed duct or infection. "PCR-DNA sequence revealed nucleotide sequence differences in the PRDX6 and NDUFS6 genes among control and mastitis-affected she-camels." (PMID 40711280, 2025).
Non-alcoholic fatty liver disease (1 paper, 2017). "NDUFA8 (Cluster 5), NDUFS6, and GSK3B (Cluster 2) were mapped to “Non-alcoholic fatty liver disease (NAFLD)”." (PMID 28445522, 2017).
Nystagmus (1 paper, 2024). Rhythmic, involuntary oscillations of one or both eyes related to abnormality in fixation, conjugate gaze, or vestibular mechanisms. "Because medication-induced nystagmus was excluded in our patients, it is possible that NDUFS6 defects cause dysfunction of neural structures involved in repetitive eye movements including the vestibulocerebellum or its connections with the brainstem." (PMID 38459834, 2024).
Parkinson disease (1 paper, 2023). A progressive degenerative disorder of the central nervous system characterized by loss of dopamine producing neurons in the substantia nigra and the presence of Lewy bodies in the substantia nigra and locus coeruleus. "Furthermore, this study shed light on the altered gene expression of CTNNB1, NDUFS6, and CAV1 in PBMC, which could serve as biomarkers for detecting pesticide-related Parkinson’s disease." (PMID 37508933, 2023).
pneumonia (1 paper, 2025). An acute, acute and chronic, or chronic inflammation focally or diffusely affecting the lung parenchyma, caused by an infection in one or both of the lungs (by bacteria, viruses, fungi, or mycoplasma.). "Using PCR-DNA sequence verdicts, the IL-1α (356-bp), IL-1β (423-bp), IL-6 (384-bp), TNFα (490-bp), IL-10 (306-bp), IFN-γ (321-bp), PRDX6 (434-bp), ATG7 (416-bp), NDUFS6 (405-bp), and NOX4 (396-bp) genes were found to have different SNPs in the amplified DNA bases linked to pneumonia." (PMID 40711280, 2025). "Our investigation used a PCR-DNA-sequencing procedure to illustrate the difference in immunological (IL-1α, IL1B, IL6, TNF-α, IL10, and IFN-γ) and antioxidant (PRDX6, ATG7, NDUFS6, and NOX4) genes in calves with pneumonia and healthy calves." (PMID 40711280, 2025).
prostatitis (1 paper, 2025). An infectious or non-infectious inflammatory process affecting the prostate gland. "We revealed two Tier 2 genes (NOA1 and ELAC2) and one Tier 3 gene (ACAT1) for BPH, two Tier 3 genes (TRMU and SFXN5) for prostatitis, and six Tier 3 genes (MRPL24, NDUFS6, PUS1, NBR1, GLOD4, and PCBD2) for PCa." (PMID 40919435, 2025). "Our analysis revealed two Tier 2 genes (NOA1 and ELAC2) for BPH, two Tier 3 genes (TRMU and SFXN5) for prostatitis, and six Tier 3 genes (MRPL24, NDUFS6, PUS1, NBR1, GLOD4, and PCBD2) for PCa." (PMID 40919435, 2025).
renal fibrosis (1 paper, 2023). A final common manifestation of a wide variety of chronic kidney diseases characterized by glomerulosclerosis and tubulointerstitial fibrosis. "In line with this prediction, deficiency in complex I induced by interruption of Ndufs6 induced renal injury including albuminuria and renal fibrosis." (PMID 37029501, 2023).
tumor (8 papers, 2020 to 2025). "NDUFS6, part of mitochondrial respiratory chain complex I, impacts mitochondrial function and may modulate immune surveillance and tumor growth when targeted." (PMID 40919435, 2025). "This combinatorial approach elicited T cells against specific neoantigens (LNPEP, NDUFS6, MYO15, and CDK15) that were positively correlated with reduced tumor burden in the treated animals." (PMID 33723260, 2021).
neurodegenerative disease (2 papers, 2024 to 2025). A disorder of the central nervous system characterized by gradual and progressive loss of neural tissue and neurologic function. "Mutations in the NDUFS6 gene can lead to mitochondrial Complex I deficiency, which is associated with neurodegenerative diseases in adults, as well as severe illness in neonates." (PMID 40711280, 2025). "GO and KEGG analyses of ME7 also identified upregulation of genes related to mitochondrial oxidative phosphorylation, including NDUFS6, NDUFA13, NDUFB7, NDUFA3, and NDUFS5, which are involved in a variety of neurodegenerative diseases." (PMID 37971544, 2024).
peripheral neuropathy (2 papers, 2024 to 2026). A disorder affecting the peripheral nervous system. "Based on these findings, this variant can now be classified as pathogenic for peripheral neuropathy, and NDUFS6 should be considered as a novel gene for axonal CMT." (PMID 38459834, 2024).
infection (1 paper, 2025). The state of being infected such as from the introduction of a foreign agent such as serum, vaccine, antigenic substance or organism. "However, the efficacy of symptomatic treatments was not sufficient in adult Ndufs6-deficient mice, which attributed to a higher vector retention rate in liver and lower vector infection rate in cardiomyocytes." (PMID 40399258, 2025).
NDUFS6 also shares sentences with these, for which no sentence is quoted: mitochondrial disease (3 papers); Leber hereditary optic neuropathy (2); multiple myeloma (2); optic atrophy (2); Borderline intellectual disability (1); brain tumor (1); Charcot-Marie-Tooth neuropathy (1); Encephalopathy (1); epilepsy (1); hepatocellular carcinoma (1); Intellectual disability (1); lung carcinoma (1); Mitochondrial encephalopathy (1); non-small cell lung carcinoma (1); Optic neuropathy (1); osteosarcoma (1); rectal cancer (1); renal disease (1); squamous cell carcinoma (1).